IL6 (interleukin 6)
Diseases named in the same sentence as IL6 in open-access papers (continued):
Sharing a sentence is not in itself a finding about the gene and the disease.
lupus nephritis (continued). "In conclusion, sialoglyco-conjugate abnormalities, high IL-6 trans-signaling and immune anti-gangliosides response profile could be considered a mechanism involved in lupus nephritis pathogenesis." (PMID 34205600, 2021). "Our study showed that the expression level of serum IL-6 in cSLE correlated positively with the occurrence of lupus nephritis and degree of disease activity, and negatively with CD4+/CD8+, indicating a potential correlation between IL-6 and the pathogenesis of SLE." (PMID 33882880, 2021). "Interestingly, administration of neomycin from 3 to 8 weeks of age led to minimal changes in RLN weight, proteinuria and circulating IL-6, suggesting a vancomycin-specific effect on exacerbation of lupus nephritis." (PMID 33240280, 2020). "Interestingly, CaMK4 also plays a role in resident kidney cells and contributes to the pathogenesis of lupus nephritis by promoting mesangial cell proliferation through IL-6 production." (PMID 30333818, 2018). "Optimal cutoffs for diagnosing active forms of lupus nephritis using IL-6 and IL-17 were 12.3 pg/mL (AUC 93%) and 19.7 pg/mL (AUC 95%), respectively, whereas optimal cutoffs for diagnosing lupus nephritis in remission were higher, at 20.8 pg/mL (AUC 80%) and 27 pg/mL (AUC 82%), respectively." (PMID 28487810, 2017). "Similarly, IL-6 can be elevated in the urine of lupus nephritis patients, with higher levels correlating with active renal inflammation and pathology." (PMID 26579125, 2015). "Whether disease progression in patients with lupus nephritis can be suppressed by targeting IL-6 remains to be determined." (PMID 24171032, 2013). "In NZB/W mice IL-6 promotes disease, and anti-IL-6 therapy delays lupus nephritis, suggesting that IL-6 blockade might also be beneficial in SLE patients." (PMID 22500177, 2012). "Hence, in lupus nephritis, locally produced IL-6 may emerge as a biomarker for disturbed kidney function." (PMID 37189804, 2023). "Data from our in vitro studies demonstrated that induction of mTOR and ERK phosphorylation, α-smooth muscle actin, and mediators of fibrosis by IL-6 was comparable to that observed with TGF-β1, and it is plausible to suggest that IL-6 may contribute to kidney fibrosis in lupus nephritis." (PMID 35571122, 2022). "Hence, HDW might ameliorate lupus nephritis by inhibiting IL-6 secretion and STAT3-induced IL-17 expression." (PMID 35958622, 2022). "Therefore, we hypothesized that IL-6, for which a relevant role in the development of lupus nephritis in MRL-Faslpr mice has already been shown, might have an important role in vascular injury in the MRL-Faslpr mouse model." (PMID 33669022, 2021). "However, only IL18 and IL6 were higher in class IV versus class III lupus nephritis." (PMID 27738386, 2016). "In addition, only IL18 and IL6 were higher in class IV versus class III lupus nephritis." (PMID 27738386, 2016). "Indeed, the inflammatory cytokines TNF (tumor necrosis factor), Interleukin-6, and BAFF (B-cell activating factor) are associated with B-cell kidney infiltration and have been shown to contribute to disease pathogenesis in patients with lupus nephritis." (PMID 26225955, 2015). "Furthermore, at an identical anti-dsDNA IgG concentration, HK-2 cells demonstrated a more prominent induction of IL-6 secretion compared to mesangial cells, thereby highlighting the importance of proximal renal tubular epithelial cells in the immunopathogenesis of lupus nephritis." (PMID 24171032, 2013). "NEU1 is also responsible for coordinating inflammatory responses in lupus glomerulonephritis, such as the release of tumor necrosis factor-α (TNF-α) and interleukin-6 (IL-6)." (PMID 39194692, 2024). "At the same time, quercetin can protect the kidney by reducing the level of proteinuria and the expression of interleukin-6 (IL-6) and tumor necrosis factor-α (TNF-α) in lupus nephritis (LN) mice." (PMID 37026113, 2023).
lupus nephritis (continued). "Lactobacillus supplementation in a classical animal model of lupus nephritis, MRL/lpr mice, decreased IL-6 levels in the gut." (PMID 36359816, 2022). "We have investigated glycoconjugates sialization profile, endogen synthesis rate of antiganglioside antibodies (AGA), IL-6 signaling pathways correlated with activity disease in systemic lupus erythematous (SLE) and lupus nephritis (LN)." (PMID 34205600, 2021). "We found that CKD-506 significantly decreased levels of IFN-γ, IL-1β, IL-4, IL-6, IP-10, MCP-1, and CCL4 in the kidney extracts of mice with lupus nephritis." (PMID 30470828, 2018). "Proinflammatory chemokines (MCP-1) and cytokines (IL-6, TNF-α), Th1 cytokines (IL-2, IFN-γ), Th2 cytokines (IL-4, IL-10), and Th17 cytokines (IL-17A) are involved in pathogenesis of lupus nephritis, and are therapeutic targets for lupus nephritis." (PMID 27846813, 2016). "In particular, the expressions of TNF-α, IL-6 and IL-10 are markedly elevated in SLE patients with lupus nephritis." (PMID 24629023, 2014). "Serum IL-6, IL-12, TNF-α and IFN-γ levels of lupus nephritis mice treated with polysaccharide of large yellow croaker swim bladder (PLYCSB)." (PMID 24667130, 2014). "In this review, we provide an overview of the synthesis and putative roles of IL-6, TNF-α, IFN-α, and hyaluronan in the pathogenesis of lupus nephritis focusing on their effects on human mesangial cells and proximal renal tubular epithelial cells." (PMID 24171032, 2013). "Serum levels of IL-6, TNF-α, IFN-α, and hyaluronan (HA) are increased in patients with lupus nephritis." (PMID 24171032, 2013). "Expression of IL-6, TNF-α, type I IFNs, and hyaluronan are increased in the kidneys of patients and mice with active lupus nephritis and have been shown to contribute to disease pathogenesis." (PMID 24171032, 2013). "IL-6 is elevated in many SLE patients, particularly those with active disease or lupus nephritis." (PMID 41009491, 2025). "In particular, sirukumab, an anti-IL6 monoclonal antibody, has been used in active lupus nephritis; however, without good results in terms of reduction in proteinuria." (PMID 41009491, 2025). "An earlier proof-of-concept trial in lupus nephritis patients failed to establish the effectiveness of IL-6 inhibition alongside conventional therapy." (PMID 37711613, 2023). "However, quercetin reversed the expression of IL-6, IL-8, IL-33, and HMGB1 induced by IL-33, indicating that quercetin exerts anti-fibrotic and anti-inflammatory effects in the cellular model of lupus nephritis, as opposed by IL-33." (PMID 36421424, 2022). "Taken together, these results indicate that vancomycin treatment led to dampened IL-6 and IL-17 production and attenuated lupus nephritis in control mice but failed to change either the IL-17 response or disease manifestations in PP mice." (PMID 31311609, 2019). "The M1-like macrophage subtype has long been believed to be a source of pathology in lupus nephritis and the high levels of IL-6, IFN-ɣ and TNF-α found in patients with lupus nephritis support the important role of pro-inflammatory M1-like macrophages in the pathogenesis of the disease." (PMID 27091114, 2016). "The lupus nephritis that develops in TANK-KO mice, and which is driven by hyperactivation of the MyD88 signaling network, was similarly prevented by crossing to IL-6–KO mice." (PMID 27807192, 2016). "The mechanisms through which IL-6 is locally produced in the kidney during pathogenesis of lupus nephritis have not been fully defined." (PMID 24171032, 2013). "Additionally, in nephritic lesions of MRLlpr/lpr mice, TLR7 is expressed on renal macrophages and contributes to the production of pro‐inflammatory mediators, including IL‐12, IL‐6, CCL2, and IFN‐α, which is known to contribute to the progression of lupus nephritis." (PMID 28665028, 2017). "Serum IL-6 levels did not change in SLE and lupus nephritis." (PMID 37189804, 2023).
Multiple Organ Failure (82 papers, 2006 to 2026). A progressive condition usually characterized by combined failure of several organs such as the lungs, liver, kidney, along with some clotting mechanisms, usually postinjury or postoperative. "Hyperinflammation followed by a subsequent cytokine storm is associated with the high production of IL-6, which, in turn, is correlated with multiple organ failure in patients affected by SARS-CoV-2." (PMID 40076291, 2025). "IL-6 is known to play a leading role in the development of cytokine storms and associated organ and multiple organ failure." (PMID 34832856, 2021). "Released by monocytes and macrophages, IL-6 will result in an inflammatory state which causes multiple organ failure." (PMID 34020617, 2021). "While UCD is thought to be a benign disease because curative resection is possible for most patients, MCD is a life-threatening disorder involving a systemic inflammatory response and multiple organ failure caused by the overproduction of interleukin-6 (IL-6)." (PMID 34107915, 2021). "Multicentric Castleman’s disease is a life-threatening disorder involving a systemic inflammatory response and multiple organ failure caused by the overproduction of interleukin-6." (PMID 34107915, 2021). "IL-6 not only correlates with injury severity but is highly associated with multiple organ failure and outcome." (PMID 24023413, 2013). "• Low HLA-DR expression and high IL-6 and IL-10 levels in the first days after surgery were associated with multiple organ failure and death." (PMID 16899122, 2006). "Early high levels of IL-6 and IL-10 and subsequently reduced HLA-DR were all associated with multiple-organ failure and death." (PMID 16899122, 2006). "Furthermore, the elevation of serum IL-6 levels in children admitted to the PICU showed a linear relationship with an increased risk of new or progressive multiple organ failure incidence." (PMID 38672594, 2024). "In this study, elevated cystatin C levels were associated with higher IL-6 levels and comorbidities, which may illustrate an association between kidney injury and cytokine storm syndrome or multiple organ failure." (PMID 33828483, 2021). "Constantly elevated IL-6 levels have been associated with multiple organ failure and death." (PMID 33917002, 2021). "Given the dual role of IL-6, therapeutic strategies targeting this cytokine should aim to enhance its beneficial antiviral effects while preventing excessive IL-6 production to mitigate tissue damage and multiple organ failure." (PMID 40692679, 2025). "Only one patient developed Grade 5 CRS with IL‐6 levels > 5000 pg/mL and died of multiple organ failure." (PMID 40827511, 2025). "Our arguments are based on the principles that CRRT is able to remove IL‐6 from circulation thus attenuating the cytokine storm, can influence hepcidin levels, and reduction in oedema, and is often used in multiple organ failure to regain homeostasis control." (PMID 39252436, 2024). "Hyperthermia (42 °C) was refractory to acetaminophen treatment and deteriorated to multiple organ failure due to hypercytokinemia, with increased serum levels of interleukin-6 (44.6 pg/mL) and interleukin-10 (1010 pg/mL)." (PMID 35219343, 2022). "In S. aureus sepsis, cytokine storm (highly elevated TNF, IL-1, and IL6) induced by S. aureus superantigens, Lpp, PGN, and other components causes hyperinflammation, DIC, multiple organ failure, and later death." (PMID 33546401, 2021). "On the other hand, excessive increasein IL-6 after acute lung damage leads to multiple organ failure (MOF) and to acytokine storm." (PMID 33907593, 2021). "In present study, high IL-6 level is convinced of facilitating SARS-CoV-2 clearance, but inevitably causing tissue damage and even life-threating multiple organ failure during acute infection." (PMID 34088317, 2021).
Multiple Organ Failure (continued). "Cytokine storm refers to the phenomenon where a variety of cytokines in body fluid, such as TNF-α, IL-1, and IL-6, are produced rapidly after an organism is infected and is an important cause of ARDS and multiple organ failure." (PMID 32903363, 2020). "LPS results in the overexpression and release of proinflammatory cytokines, including tumor necrosis factor-α (TNF-α), interleukin-1β (IL-1β), and interleukin-6 (IL-6), which contribute to LPS-induced multiple organs failure including myocardial depression." (PMID 31315617, 2019). "IL-6 correlates with injury severity as well as the incidence of multiple organ failure and outcome." (PMID 24589345, 2014). "Excessive neutrophil and monocyte infiltration exaggerates inflammation and severe organ injury by releasing pro-inflammatory mediators, such as IL-6, which can lead to shock, multiple organ failure, and even death." (PMID 24886652, 2014). "This activation triggers inflammatory gene expression characterized by excessive cytokine release, including tumor necrosis factor-alpha, interleukin-1 beta, and interleukin-6, ultimately resulting in widespread tissue damage, increased vascular permeability, and multiple organ failure." (PMID 40941711, 2025). "Therefore, clinical data are needed to demonstrate the impact of IL-6 removal with ADVOS multi in the outcome of critically ill patients with multiple organ failure." (PMID 39083101, 2024). "Inflammatory cytokines, such as IL-6, can cause the so-called “cytokine storm”, which may be a driver of acute lung injury and ARDS, and promote the progression of tissue damage to multiple organ failure." (PMID 34167463, 2021). "According to the selected threshold, our study suggests that IL-6 levels were certainly higher than normal values in critically ill COVID-19 patients but definitely lower than other overwhelming acute inflammatory syndromes with multiple organ failure." (PMID 33382773, 2020). "IL-6 is a prognostic marker for trauma outcome and development of multiple organ failure." (PMID 25620994, 2014). "In this and other studies, the severity of multiple organ failure was related to serum IL6 levels." (PMID 23935244, 2013). "An elevated De Ritis ratio with high IL-6 levels may indicate the dysregulation of the immune response and the onset of multiple organ failure, including liver injury; therefore, this parameter might serve as a red flag indicating the exacerbation of a COVID-19 infection." (PMID 36366457, 2022). "High circulating and tissue levels of proinflammatory cytokines, such as tumor necrosis factor-alpha (TNF-α) and interleukin-6 (IL-6), appear to contribute to the development of a systemic inflammatory response that produces or aggravates lung damage and may lead to multiple organ failure." (PMID 20199666, 2010). "Monocytes control the innate immune response to microorganisms by producing inflammatory cytokines such as interleukin-6 (IL-6), IL-17, IL-1β, and SIRS, mortality and multiple organ failure are all possible outcomes." (PMID 35928365, 2022). "SARS-CoV-2 combined with ACE2 stimulated macrophages and monocytes to release proinflammatory cytokines, including IL6, NF-kB, and TNF-α, leading to inflammation-derived injurious cascades and then to multiple organ failure." (PMID 34335247, 2021). "In particular, a correlation between serum IL-6 and TNF-α level and multiple organ failure has been reported." (PMID 32079307, 2020). "These previous studies, including ours, support the present findings of the role of IL-1β in trypsin upregulation in combination with IL-6 and/or TNF-α, and also on the role of trypsin in the induction of various signal transductions in multiple organ failure." (PMID 27714503, 2017). "Clinical studies revealed that the levels of TNF-α, IL-1β, and IL-6 in BALF and plasma of patients with ALI/ARDS increased and were correlated with the pathogenesis of multiple organ failure." (PMID 23586067, 2013).
Multiple Organ Failure (continued). "Classical inflammatory pathways investigated in the pathogenesis of trauma multiple organ failure such as IL-6, IL-8, and IL-10 were not differentially expressed in patients who would later develop MODS." (PMID 28715416, 2017). "Initiation of therapy within 24 h of septic shock might be the key, as hemadsorption did not reduce mortality or lower plasma IL-6 levels in the presence of multiple organ failure." (PMID 36431292, 2022).
systemic sclerosis (81 papers, 2009 to 2026). A chronic disorder, possibly autoimmune, marked by excessive production of collagen which results in hardening and thickening of body tissues. "To date, only two small molecule drugs, Nintedanib and Pirfenidone, have been approved for IPF, while Tocilizumab, an anti-IL-6 biologic, is approved for systemic sclerosis-associated interstitial lung disease (SSc-ILD), a related pathology." (PMID 38976646, 2024). "The association of systemic sclerosis and other autoimmune diseases with cytokine dysregulation, including hyperproduction of IL-6, has been well-established." (PMID 39676864, 2024). "Interleukin-6 (IL-6) plays a key pathogenic role in experimental models of systemic sclerosis and graft-versus-host diseases." (PMID 37206922, 2023). "Neutralizing, leads to decreased CRP levels, increased susceptibility to infection.May form stable complexes with IL-6 and contribute to disease progression in systemic sclerosis." (PMID 31354706, 2019). "Indeed, serum IL-6 has been shown to be predictive of early functional decline and mortality in interstitial lung disease associated with systemic sclerosis." (PMID 27459687, 2016). "In addition to chemokines, cytokines such as IL-6 or TGF-β also can mediate different pathogenic processes in systemic sclerosis." (PMID 19615053, 2009). "Clinically, high serum IL-6 levels in early systemic sclerosis-ILD predict a decline in lung function and increased mortality, suggesting that IL-6 is a biomarker of the immune-fibrotic phenotype." (PMID 41465549, 2025). "IL-6 plays a crucial role in systemic sclerosis (SS) by contributing to vascular damage and fibrosis development." (PMID 41009491, 2025). "A recent study found that ECM markers such as C3M and C4M were reduced in patients with scleroderma and systemic sclerosis (SSC) following treatment with anti-IL6 drug tocilizumab." (PMID 40142664, 2025). "For instance, in systemic sclerosis (SSc), an autoimmune disease, interleukins such as IL-6, IL-23, IL-10, and IL-17 secreted by B cells or T cells are known to play crucial roles in the pathogenesis." (PMID 39562488, 2025). "Notably, clinical findings from a study involving 102 individuals with systemic sclerosis (SSc) demonstrated heightened IL-6 gene expression in carriers of the G allele." (PMID 38790215, 2024). "LINC02381/hsa-let-7f-5p/IL-6 competitive network in another immune-mediated connective tissue disease systemic sclerosis (SSc) was shown to be potentially involved in inflammatory and immune processes immune microenvironmental variation." (PMID 38376769, 2024). "Interleukin-6 (IL-6), recognized as one of the most potent proinflammatory cytokines, assumes a distinctive role in the progression of systemic sclerosis, contributing significantly to both vascular damage and fibrosis development." (PMID 38790215, 2024). "Inhibition of IL-6 has shown promise in preventing early lung disease progression in patients with systemic sclerosis." (PMID 39676864, 2024). "Paclitaxel and docetaxel can lead to an increase in serum IL-6 levels, which can mediate endothelial cell activation and apoptosis in patients with systemic sclerosis (SSc) and participate in the early stages of SSc development." (PMID 37768354, 2023). "Both IL-6 and TNFα are also being evaluated in clinical trials as potential drug targets for the treatment of systemic sclerosis." (PMID 37228128, 2023). "In vitro treatment of ibrutinib in peripheral blood from systemic sclerosis reduces IL-6 and TNF-α production, while IL-10 is preserved." (PMID 36521376, 2022). "Other researchers showed that SC decreased the production of IL-6, IL-8 and ROS in dermal fibroblast cultures isolated from patients with systemic sclerosis." (PMID 34768607, 2021).